INS (insulin)
Diseases named in the same sentence as INS in open-access papers (continued):
Sharing a sentence is not in itself a finding about the gene and the disease.
diabetes (continued). "However, we associated Coprococcus with both diabetes status and insulin and hypoglycemic drugs; this genus has been previously associated with metformin intake in the LifeLines-DEEP population-based metagenomic study." (PMID 34915914, 2021). "There has been some suggestion that insulin therapy itself may cause cardiac dysfunction and this could contribute to the excess risk of heart failure amongst those with diabetes." (PMID 33889602, 2021). "Some researchers believe that the epidermal structural barrier in the skin of diabetes patients is damaged and prolonged hyperglycemic stimulation and insulin deficiency inhibit keratinocyte proliferation and directional migration, interfering with epidermal differentiation." (PMID 34777244, 2021). "The relationship between circulating insulin and weight gain may contribute to this protective effect given peripheral insulin and insulin therapy in the context of diabetes is associated with weight gain." (PMID 32920595, 2021). "Overall, these results provide remarkable evidence that improvements in glycaemic control with insulin therapy could assist in the recovery from diabetes-associated ED." (PMID 34198786, 2021). "Some studies confirmed the susceptibility of diabetics, especially if insulin-dependent." (PMID 34093229, 2021). "In addition, carnitine deficiency in this model of diabetes is a factor linked to a reduction in glucose use, a metabolic aberration accompanied by increased ischemic injury to the heart and peripheral insulin resistance." (PMID 34833964, 2021). "However, when diabetes patients administer insulin, there is a risk of hypoglycaemia occurring if blood glucose levels are reduced excessively." (PMID 34762125, 2021). "Volpe suggests that if magnesium supplementation affects insulin sensitivity in participants with diabetes mellitus, it may also improve insulin sensitivity in obese individuals at risk of type 2 diabetes mellitus." (PMID 35008602, 2021). "New studies targeting the proteins that control mitochondrial Ca2+ uptake should reveal whether altered insulin secretion is causally related to diabetes progression and could potentially expand the repertoire of therapeutic tools to treat this disease." (PMID 33802289, 2021). "Babies with early diabetes usually exhibit mutations in the gene encoding insulin." (PMID 35141228, 2021). "Finally, we also tested the association of GRS with insulin secretion and resistance as well as postpartum diabetes." (PMID 34801028, 2021). "Current NICE guidelines advise against the use of CSII for people with T2D 67, and a consensus statement from ADA and European Association for the Study of Diabetes (EASD) in 2018 only briefly referred to a limited role for insulin pumps in a minority of people with T2D23." (PMID 33950566, 2021). "Type 1 diabetes mellitus (T1DM) is caused by an absolute deficiency of insulin secretion." (PMID 33435282, 2021). "High levels of soluble fiber and other bioactive components of flaxseeds help in maintaining normal plasma glucose levels and have a protective effect against diabetes risk by affecting insulin secretion and the mechanism through which insulin performs its function." (PMID 34540481, 2021). "Diabetes is defined by the American Diabetes Association (ADA) as a group of metabolic diseases characterized by hyperglycemia due to defects in the secretion of insulin, its action, or both." (PMID 35096863, 2021). "The most common forms of diabetes mellitus are type 1 diabetes, in which there is an absolute deficiency of insulin due to the damage of pancreatic beta cell destruction, and type 2 diabetes mellitus, in which insulin resistance may lead to hyperglycemia." (PMID 33478081, 2021). "Diabetes mellitus involving a defect in insulin secretion causes severe complications." (PMID 34881312, 2021).
diabetes (continued). "Diabetes mellitus (DM), more simply called diabetes, is an endocrine disorder caused by a defect in the pancreas that prevents the production of insulin or its inefficient use by the body, resulting in hyperglycemia that, over time, leads to severe health complications." (PMID 33995021, 2021). "Type 2 diabetes mellitus is determined by several factors, including pancreas β-cell dysfunction, insulin resistance, increased hepatic and intestinal glucose production, or deficient insulin secretion." (PMID 34451706, 2021). "It is hypothesized that Mg supplementation would improve glucose and insulin outcomes in those with diabetes and in those with conditions that put them at a high risk of developing diabetes." (PMID 34836329, 2021). "Furthermore, both of these molecules are involved in increasing insulin sensitivity of different tissues, and thereby, improving health outcomes associated with insulin resistant, such as diabetes mellitus and reproductive disorders." (PMID 33498674, 2021). "Diabetes mellitus (DM) is a chronic disease that causes hyperglycemia because of impaired insulin secretion by pancreatic beta cells and peripheral insulin resistance, which may lead to serious complications." (PMID 34674696, 2021). "While insulin has been identified as a critical autoantigen, the list of diabetes-associated autoantigens continues to grow and now includes post-translationally modified neoepitopes and hybrid insulin peptides, generated at the site of autoimmune attack in the islet." (PMID 33418839, 2021). "However, previous investigations have not simultaneously analyzed the effect of changes in both galectin-3 and adiponectin concentrations on the risk of diabetes and insulin sensitivity and secretion." (PMID 34096884, 2021). "Although our understanding of the dynamics of protein S-acylation of the key proteins discussed in this review is limited, it is interesting to note that thioesterase enzymes that mediate deacylation of BK channels have been linked to insulin secretion and diabetes." (PMID 33784857, 2021). "Diabetes mellitus (DM) is a chronic metabolic disorder, characterized by hyperglycemia and glucose, protein, and fat metabolism disturbances which causes failure in insulin production, insulin action, or both." (PMID 34262712, 2021). "A hypothesis has emerged that reduced insulin clearance is a major contributor to insulin resistance and therefore represents an independent risk factor for diabetes." (PMID 34206745, 2021). "For example, insulin sensitivity in diabetes treatment could be associated with the expression pattern of specific miRNAs and therefore, hypothetically, synthetic miRNA agents can be used to manipulate drug resistance in diabetes treatment." (PMID 34830046, 2021). "Whether exogenous insulin used for hyperglycemic control in the diabetes patients may cause an increased risk of cancer, including GCa, is an important clinical issue that has been researched for years." (PMID 34356646, 2021). "Diabetes is a chronic metabolic disorder that is identified by an abnormal blood glucose level, which is caused by either ineffective utilization or insufficient production of insulin." (PMID 33806973, 2021). "STZ-induced diabetes and pancreatic injury were confirmed, respectively, by the induction of hyperglycemia and loss of pancreatic cellular architecture (diminution of islets of Langerhans' size and insulin content) compared to the control mice." (PMID 34926699, 2021). "Some clinical studies suggested that patients with diabetes mellitus might develop poorer glycemic control, requiring the use of insulin, and have an increased risk of tuberculosis infection when they are diagnosed with GCa." (PMID 34356646, 2021). "We hypothesized that insulin analogues are associated with lower rates of hypoglycemia, greater dose flexibility, and higher treatment satisfaction among patients with type 1 diabetes mellitus." (PMID 33905628, 2021).
diabetes (continued). "Interestingly, the relative abundance of Collinsella was shown to be associated with type 2 diabetes mellitus including a positive correlation with circulating insulin levels, rheumatoid arthritis, and cholesterol metabolism." (PMID 34444813, 2021). "Hence, estrogen inhibition can lead to insulin resistance and suppress insulin secretion, whereas estrogen replacement in postmenopausal women was shown to decrease diabetes risk in previous studies." (PMID 34577625, 2021). "However, glucose and lipid metabolism disorders caused by defects in insulin secretion and reduced responses to insulin-stimulated glycometabolism are the main pathological features of diabetes." (PMID 34356130, 2021). "Additional studies should explore molecular or epigenetic mechanisms underlying the therapeutic effects of GA on diabetes-related dysfunction; especially, its role in adipogenesis, insulin signaling, and oxidative damage within adipocytes or hepatocytes should be examined." (PMID 35052597, 2021). "Sulfation is already known to play a role in pancreatic islets, where in that glycolipid sulfatides are involved in normal insulin secretion and sulfation of heparin sulfate has been implicated in islet amyloid polypeptide aggregation in type 2 diabetes mellitus." (PMID 33581409, 2021). "Being at higher risk for diabetes may increase susceptibility to insulin resistance, thus impairing the action of insulin mediated glucose disposal." (PMID 34863205, 2021). "Thus, insulin signaling in the central nervous system is of significant interest because of the global increase in the incidence of diabetes mellitus as well as the associated metabolic and neuronal comorbidities." (PMID 33906971, 2021). "Type 1 diabetes mellitus (T1DM) is based on autoimmune beta cell destruction, leading to absolute insulin deficiency, whereas type 2 diabetes mellitus (T2DM) is based on a progressive loss of beta cell insulin secretion based on the background of insulin resistance." (PMID 33605889, 2021). "Diabetes mellitus (DM) is a metabolic disease, now prevalent worldwide, characterized by chronic hyperglycemia, accompanied by disorders of glucose, adipose tissue, and protein metabolism, which are caused by defects in insulin secretion or action." (PMID 33995278, 2021). "While the American Diabetes Association states that: “Type 2 diabetes is due to a progressive loss of b-cell insulin secretion frequently on the background of insulin resistance”, WHO at least acknowledges that it is: “commonly associated with overweight and obesity”." (PMID 33555509, 2021). "Loss of beta cell mass (BCM) and decreased sensitivity to insulin underlie diabetes pathogenesis." (PMID 33800801, 2021). "Moreover, in ACACB knockout mice, continuous fatty acid oxidation increases insulin sensitivity, and feeding them a high fat/high carbohydrate diet is more likely to cause obesity and diabetes." (PMID 34573356, 2021). "Metformin, which is an insulin sensitizer, has been shown to ameliorate endothelial function with a significant association between endothelial function and insulin resistance following treatment in patients with type 2 diabetes mellitus." (PMID 34439553, 2021). "Variants in this gene have been associated with inappropriate insulin secretion from pancreatic β-cells and mutations in other subunits, which affect eIF2 signaling, have been associated with early onset diabetes." (PMID 33763119, 2021). "3-HIB is a catabolic intermediate of the BCAA valine, secreted from muscle cells, promotes muscle lipid accumulation and insulin resistance in animals, it may cause diabetes as a bioactive signaling metabolite." (PMID 34960119, 2021). "However, during diabetes, the insufficient or impaired insulin functions or both, caused lipids to catabolise and contributes it carbon atoms to the body and thus contribute to rise in blood sugar." (PMID 33958963, 2021). "Fasting insulin and HbA1C represent a proxy marker of insulin resistance and diabetes risk." (PMID 33918016, 2021).
diabetes (continued). "The Akita strain is a mouse model of insulin-deficient and monogenic diabetes." (PMID 33667544, 2021). "According to the American Diabetes Association definition, diabetes mellitus is a group of chronic metabolic diseases characterized by abnormal metabolism of carbohydrates secondary to defects in insulin secretion, action, or both, resulting in high levels of glucose in the blood." (PMID 33467038, 2021). "In addition to the known defects in insulin secretion described in CF, they determined that the loss of first phase insulin secretion is more pronounced in INDET relative to other non-diabetes glucose tolerance categories." (PMID 34868882, 2021). "By improving insulin sensitivity, vitamin K lowers diabetes risk." (PMID 33917442, 2021). "Furthermore, the compromised function of insulin is the leading cause of Diabetes Mellitus (DM) which is usually accompanied by aberrant testosterone levels." (PMID 34367061, 2021). "Therefore, IRF3 deficiency results in impaired glucose homeostasis and insulin sensitivity, which eventually leads to the development of diabetes around the age of 8 months." (PMID 34091599, 2021). "Similarly, GCK, which is the key factor in glycolysis, can also regulate insulin secretion and glucose metabolism of the liver, and loss of its activity can lead to diabetes." (PMID 33922631, 2021). "In addition, inflammatory actions cause insulin dysfunction, diabetes progression, and amplified oxidative stress." (PMID 34299638, 2021). "Compared to control islets, islets of patients with diabetes mellitus (DM) show reduced glucose stimulated insulin secretion (GSIS), which was associated with lower ATP/ADP ratio, decreased mitochondrial membrane potential, and downregulation of expression of genes associated with energy metabolism." (PMID 33546200, 2021). "Despite important advances in the manufacturing of insulin agents, insulin administration and glucose monitoring, hypoglycaemia remains the most frequent adverse event in people with diabetes treated with insulin and is associated with increased morbidity and mortality." (PMID 33566134, 2021). "This form of diabetes may have insulin levels that appear normal or increased that cause the inability of insulin to control hyperglycemia and lipid metabolism, and even β-cell function may be normal." (PMID 34037093, 2021). "In a previous systematic review and meta-analysis, it was reported that Mg supplementation, compared to placebo, improves several glucose and insulin-sensitivity parameters in people affected by diabetes or have conditions (such as obesity) that put them at increased risk of developing diabetes." (PMID 34836329, 2021). "Furthermore, another study found that after multivariable adjustment, T2DM subjects treated with insulin suffered a higher risk of all-cause mortality though bias cannot be excluded, as insulin was more likely to be used in subjects with more severe diabetes." (PMID 33598483, 2021). "Obesity and hyperglycemia are associated with reduced brain insulin transport, whereas higher triglycerides (studied in starved obese mice) and diabetes (when induced acutely in mice with streptozotocin) seem to be associated with higher brain insulin transport." (PMID 33917464, 2021). "Diabetes mellitus is a common endocrine disease in dogs, with the most frequent presentation being that of insulin deficiency with a life-long requirement for exogenous insulin." (PMID 33323126, 2020). "Reduction in insulin secretory function in Asians relative to insulin resistance may contribute to increased risk of diabetes." (PMID 32153503, 2020). "The insulin signaling pathway is closely linked to metabolic change, and the manifestation of decreased brain energy metabolism caused by insulin resistance is similar to diabetes." (PMID 33250703, 2020).
diabetes (continued). "Another study in Germany showed that individuals with higher genetic risk for diabetes, such as those with altered insulin sensitivity, were more susceptible to the exposure of PM10 where the odds of diabetes increased by 8% per risk allele and 35% per 10 μg/m3 exposure to PM10." (PMID 32245482, 2020). "PRAS40 in conjunction with mTOR is closely associated with diabetes, cardiovascular diseases, and neurological diseases, such as improving insulin sensitivity, decreasing cardiomyocyte apoptosis after myocardial infarction and neuroprotectivity after transient focal cerebral ischemia." (PMID 33062146, 2020). "Resistance of cells to insulin or impair in insulin synthesis is the underlying causes of diabetes." (PMID 32509990, 2020). "In the case of diabetes, it may be linked to impaired insulin secretion (insulin deficiency), impaired insulin action (insulin resistance), or both." (PMID 32982969, 2020). "The onset of diabetes involves several processes, varying from the autoimmune destruction of the pancreatic beta (β)-cells responsible for insulin production to abnormalities that cause insulin action resistance." (PMID 33255455, 2020). "Diabetes mellitus is a chronic metabolic disease that causes abnormally high levels of blood sugar (hyperglycemia) due to a failure in insulin production by pancreas or when the body cannot use insulin effectively." (PMID 32294991, 2020). "There is evidence that skeletal muscle mitochondrial respiration can affect insulin sensitivity, although it is unclear whether mitochondrial dysfunction is a cause or consequence of insulin resistance in type 2 diabetes mellitus." (PMID 32539156, 2020). "MFN2 expression has also been inversely linked with ER stress, insulin signaling and diabetes." (PMID 32141474, 2020). "In addition, diabetes is a well-known risk factor for cerebrovascular disease and it is related to glucose toxicity, abnormalities in cerebral insulin homeostasis, and microvascular abnormalities." (PMID 33282807, 2020). "Evidently, our observed susceptibilities of distinct insulin granule subpopulations to the diabetes-mimicking treatments correlate well with previous clinical observations showing that the same respective granule specific markers are co-released with insulin in T1D and T2D patients." (PMID 33164744, 2020). "Duration of diabetes, use of insulin, and obesity were also associated with poor HRQL." (PMID 32248877, 2020). "One month of insulin treatment of animals with 3‐months of diabetes normalized the levels of a majority of these metabolites to those of non‐diabetic, age‐matched controls (112 of the 171 (65.5%), although insulin did cause change levels of an additional small number of metabolites (less than 6%)." (PMID 33200530, 2020). "There is evidence that sweet foods do hit the pleasure and reward centres in the brain rather like hard drugs... leads to insulin resistance (where insulin becomes less effective), high blood pressure, diabetes and unhealthy cholesterol levels—all risk factors for cardiac disease." (PMID 31951616, 2020). "We suppose that, in our trial, worse prognosis associated to metformin and/or insulin administration could be related to diabetes as comorbid condition." (PMID 35582045, 2020). "Diabetes mellitus is classified into type 2 diabetes mellitus, which develops because of inadequate insulin secretion and resistance, and type 1 diabetes mellitus, which occurs as a result of insulin depletion caused by the destruction of pancreatic β-cells by the body’s own immune system." (PMID 33255983, 2020). "Diabetes is a chronic condition affecting over 400 million worldwide and is characterized by a relative or absolute insulin insufficiency associated with a loss of insulin secreting pancreatic β-cells." (PMID 32601405, 2020).